C1QTNF9B (C1q and TNF related 9B)
Description:
Probable adipokine. Activates AMPK, AKT, and p44/42 MAPK signaling pathways.
Synonyms: CTRP9B
Tractability: Antibody: UniProt places it where antibodies can reach, with high confidence; UniProt predicts a signal peptide or a membrane-spanning region; its Gene Ontology location is reachable by antibodies, with medium confidence.
Gene: Protein-coding gene on chromosome 13 (23,891,099 to 23,897,502, reverse strand). Ensembl gene ENSG00000205863.
Subcellular location: Secreted
Gene Ontology:
Molecular function: protein binding
Cellular component: extracellular region
Genetic constraint (gnomAD): Loss-of-function variants: 10 observed, 11.99 expected, observed/expected ratio (o/e) 0.83, 90% interval 0.51 to 1.41. The synonymous counts are far from expectation, so gnomAD's model fits this gene poorly and the ratio says little. Missense variants: 166 observed, 307.11 expected, observed/expected ratio (o/e) 0.54, 90% interval 0.47 to 0.62. Synonymous variants: 67 observed, 112.89 expected, observed/expected ratio (o/e) 0.59, 90% interval 0.49 to 0.73.
Homologues: Orthologues: macaque C1QTNF9 (94% identical), dog ADIF1 (88% identical), rabbit ADIF1 (86% identical), guinea pig ADIF1 (85% identical), mouse C1qtnf9 (83% identical), rat C1qtnf9 (83% identical), zebrafish c1qtnf9 (55% identical), tropical clawed frog c1qtnf9b (35% identical). Paralogues in human: C1QTNF9 (98% identical), COL8A2 (41% identical), COL10A1 (40% identical), COL8A1 (38% identical), OTOL1 (36% identical), C1QTNF7 (35% identical), ADIPOQ (34% identical), C1QTNF2 (34% identical), C1QTNF5 (29% identical), C1QB (27% identical), C1QC (27% identical), C1QL2 (25% identical), and 11 more.
Diseases named in the same sentence as C1QTNF9B in open-access papers:
C1QTNF9B is named in the same sentence as 1 disease in open-access papers, as found by Europe PMC text mining. Sharing a sentence is not in itself a finding about the gene and the disease.
C1QTNF9B shares sentences with these, for which no sentence is quoted: cancer (2 papers).